ZCWPW1 (zinc finger CW-type and PWWP domain containing 1)
Description:
Dual histone methylation reader specific for PRDM9-catalyzed histone marks (H3K4me3 and H3K36me3). Facilitates the repair of PRDM9-induced meiotic double-strand breaks (DSBs) (By similarity). Essential for male fertility and spermatogenesis (By similarity). Required for meiosis prophase I progression in male but not in female germ cells (By similarity).
Synonyms: FLJ10057; DKFZp434N0510; ZCW1
Tractability: PROTAC: ubiquitination databases record sites on it.
Gene: Protein-coding gene on chromosome 7 (100,400,826 to 100,428,992, reverse strand). Ensembl gene ENSG00000078487.
Subcellular location: Nucleus; Chromosome
Subcellular location (Human Protein Atlas): Golgi apparatus
Gene Ontology:
Molecular function: histone H3K4me3 reader activity; zinc ion binding
Biological process: epigenetic regulation of gene expression; homologous chromosome pairing at meiosis; meiosis I; positive regulation of DNA recombination; positive regulation of double-strand break repair; spermatogenesis
Cellular component: nucleus; chromosome
Genetic constraint (gnomAD): Loss-of-function variants: 53 observed, 81.88 expected, observed/expected ratio (o/e) 0.65, 90% interval 0.52 to 0.81. The upper end of that interval is the gene's LOEUF score, 0.81, which puts it in group 3 of 6, group 1 being the genes least tolerant of losing a copy. Missense variants: 642 observed, 800.38 expected, observed/expected ratio (o/e) 0.8, 90% interval 0.75 to 0.86. Synonymous variants: 249 observed, 287.1 expected, observed/expected ratio (o/e) 0.87, 90% interval 0.78 to 0.96.
Homologues: Orthologues: chimpanzee ZCWPW1 (99% identical), macaque ZCWPW1 (94% identical), pig ZCWPW1 (71% identical), dog ZCWPW1 (69% identical), rabbit ZCWPW1 (69% identical), mouse Zcwpw1 (59% identical), rat Zcwpw1 (57% identical), tropical clawed frog zcwpw1 (18% identical). Paralogues in human: ZCWPW2 (12% identical).
Diseases named in the same sentence as ZCWPW1 in open-access papers:
ZCWPW1 is named in the same sentence as 13 diseases in open-access papers, as found by Europe PMC text mining. Sharing a sentence is not in itself a finding about the gene and the disease. The quoted sentences say what the papers report.
Alzheimer disease (4 papers, 2017 to 2025). A progressive, neurodegenerative disease characterized by loss of function and death of nerve cells in several areas of the brain leading to loss of cognitive function such as memory and language. "Other known Alzheimer's disease–associated genes, BIN1, TREM2, ZCWPW1, and APH1B, were also replicated in our time-to-event GWAS." (PMID 40949174, 2025).
Insulin resistance (3 papers, 2023 to 2025). Increased resistance towards insulin, that is, diminished effectiveness of insulin in reducing blood glucose levels. "Given that AD has been characterized as a metabolic disease influenced in part by insulin resistance, zinc finger CW-type PWWP domain protein 1 (ZCWPW1), which is involved in positively regulating DNA metabolism, may reduce the risk of late-onset AD by suppressing insulin resistance." (PMID 39000382, 2024).
male infertility (2 papers, 2024). The inability of the male to effect fertilization of an ovum after a specified period of unprotected intercourse. "In mice, the deletion of Zcwpw1 leads to male infertility, impedes the meiotic progression of spermatocytes, and results in defects in double-strand break (DSB) repair and homologous recombination." (PMID 39511641, 2024). "This is the first ever report of ZCWPW1 gene in human male infertility, and it provides valuable information for genetic counseling and diagnosis for OAT." (PMID 38310235, 2024). "In order to better understand its role in male infertility, it is worthwhile to explore the interaction of ZCWPW1 with other related genes and signaling pathways which are crucial for reproductive development." (PMID 38310235, 2024).
Azoospermia (1 paper, 2024). Absence of any measurable level of sperm,whereby spermatozoa cannot be observed even after centrifugation of the semen pellet. "ZCWPW1 is a reader of dual histone methylation, specific for obstructive azoospermia patient PRDM9-catalyzed histone marks H3K4me3 and H3K36me3, and maintaining H3K9ac level around recombination hotspots." (PMID 38310235, 2024).
lung carcinoma (1 paper, 2021). "Importantly, we observed that four of the five genes (STAG3, PODXL2, NHLRC1, and ZCWPW1) identified from our analysis in lung cancer models were significantly upregulated upon loss of MGA." (PMID 34236315, 2021).
ovarian insufficiency (1 paper, 2020). "In contrast, Zcwpw1 KO females are initially fertile, but suffer from ovarian insufficiency as they age, likely due to delayed meiosis in fetal ovaries." (PMID 32352380, 2020).
psychosis (1 paper, 2026). "Associations with APOE and MS4A for affective dysregulation, ZCWPW1, EPHA1, and BIN1 for psychosis-related symptoms, and NME8 for apathy highlight the possibility that MBI domains represent clinically observable phenotypes of underlying genetic susceptibilities." (PMID 41591092, 2026).
ZCWPW1 also shares sentences with these, for which no sentence is quoted: metabolic disease (3 papers); amyotrophic lateral sclerosis (1); colorectal cancer (1); genetic generalized epilepsy (1); infertile (1); neurological disorder (1).